ARSA (arylsulfatase A)
Description:
Lysosomal enzyme that catalyzes the hydrolysis of cerebroside-3-sulfate (sulfatide) into cerebroside and sulfate, a reaction that requires the activator protein saposin B.
Synonyms: ASA; MLD
Tractability: Small molecule: a structure with a bound ligand is known. Antibody: its Gene Ontology location is reachable by antibodies, with high confidence; UniProt predicts a signal peptide or a membrane-spanning region. PROTAC: its protein half-life has been measured.
Target class: Enzyme; Hydrolase
Gene: Protein-coding gene on chromosome 22 (50,622,754 to 50,628,177, reverse strand). Ensembl gene ENSG00000100299.
Subcellular location: Endoplasmic reticulum; Lysosome
Subcellular location (Human Protein Atlas): Golgi apparatus; Cytosol; Mid piece
Pathways (Reactome):
Immune System: Neutrophil degranulation
Metabolism: Glycosphingolipid catabolism
Metabolism of proteins: The activation of arylsulfatases
Gene Ontology:
Molecular function: calcium ion binding; cerebroside-sulfatase activity; protein binding; sulfuric ester hydrolase activity; arylsulfatase activity
Biological process: sphingolipid catabolic process
Cellular component: endoplasmic reticulum; extracellular exosome; azurophil granule lumen; endolysosome lumen; endoplasmic reticulum lumen; extracellular region; lysosomal lumen; lysosome
Genetic constraint (gnomAD): Loss-of-function variants: 33 observed, 37.85 expected, observed/expected ratio (o/e) 0.87, 90% interval 0.66 to 1.17. The upper end of that interval is the gene's LOEUF score, 1.17, which puts it in group 5 of 6, group 1 being the genes least tolerant of losing a copy. Missense variants: 685 observed, 645.99 expected, observed/expected ratio (o/e) 1.06, 90% interval 1 to 1.13. Synonymous variants: 303 observed, 280.41 expected, observed/expected ratio (o/e) 1.08, 90% interval 0.98 to 1.19.
Gene-disease validity (ClinGen):
ClinGen rates the evidence that ARSA causes each of these diseases.
metachromatic leukodystrophy (autosomal recessive): Definitive. A rare lysosomal storage disorder characterized by intralysosomal accumulation of sulfatides in various tissues, leading to progressive deterioration of motor and neurocognitive function.
Homologues: Orthologues: chimpanzee ARSA (99% identical), macaque ARSA (96% identical), pig ARSA (89% identical), rabbit ARSA (89% identical), mouse Arsa (85% identical), rat Arsa (85% identical), guinea pig ARSA (83% identical), dog ARSA (79% identical), tropical clawed frog arsa (55% identical), zebrafish arsa (55% identical), tropical clawed frog arsa.2 (55% identical), Drosophila melanogaster CG32191 (24% identical), and 7 more. Paralogues in human: GALNS (36% identical), ARSG (36% identical), STS (34% identical), ARSF (32% identical), ARSD (32% identical), ARSL (32% identical), ARSH (32% identical), ARSI (27% identical), SGSH (26% identical), ARSB (26% identical), ARSJ (23% identical), IDS (22% identical), and 4 more.
Diseases named in the same sentence as ARSA in open-access papers:
ARSA is named in the same sentence as 85 diseases in open-access papers, as found by Europe PMC text mining. Sharing a sentence is not in itself a finding about the gene and the disease. The quoted sentences say what the papers report.
metachromatic leukodystrophy (168 papers, 2006 to 2025). "Metachromatic leukodystrophy (MLD) is an inherited demyelinating disorder caused by a deficiency of ARSA." (PMID 41155400, 2025). "Metachromatic leukodystrophy (MLD) is an inherited disease caused by a deficiency of the enzyme arylsulfatase A (ARSA)." (PMID 38916435, 2025). "Metachromatic leukodystrophy (MLD) is a rare autosomal recessive lysosomal storage disorder caused by disease-causing variants in the gene coding for arylsulfatase A, leading to deficient enzyme activity and subsequent accumulation of sulfatides." (PMID 40577679, 2025). "Metachromatic leukodystrophy is an autosomal recessive disorder caused by mutations in the arylsulfatase A (ARSA) gene." (PMID 40076831, 2025). "Biallelic ARSA pathogenic variants cause metachromatic leukodystrophy, while heterozygous ARSA variants were first linked to PD in 2019." (PMID 41465155, 2025). "Among these couples, Couples 12, 55, and 185 belonged to MAR-group C. Couple 12 had a child diagnosed with metachromatic leukodystrophy, with genetic testing confirming that both parents carried P variants in the ARSA gene." (PMID 40421383, 2025). "Metachromatic leukodystrophy (MLD) is a lysosomal storage disorder caused by mutations in the arylsulfatase A gene (ARSA) and categorized into three subtypes according to age of onset." (PMID 37480112, 2023). "Metachromatic leukodystrophy (MLD) develops as a result of mutations in the arylsulfatase A (ARSA) gene." (PMID 36835039, 2023). "Arylsulfatase A Deficiency, also known as metachromatic leukodystrophy (MLD), is an autosomal recessive disorder in which the partial or complete absence of arylsulfatase A leads to demyelination of the central and peripheral nervous systems." (PMID 37761400, 2023). "Metachromatic leukodystrophy (MLD) is a neurodegenerative lysosomal storage disease caused by a deficiency in the arylsulfatase A (ARSA)." (PMID 36848337, 2023). "Initially, homozygous or compound heterozygous mutations in ARSA can lead to metachromatic leukodystrophy, an autosomal recessive lysosomal storage disease." (PMID 37865667, 2023). "Metachromatic leukodystrophy (MLD) is a lysosomal disorder caused by recessive mutations in the arylsulfatase A gene (ARSA), encoding arylsulfatase A enzyme (ASA)." (PMID 37525026, 2023). "Metachromatic leukodystrophy (OMIM: 250100) is a genetic disorder caused by mutations in the ARSA (OMIM: 607574) that result in deficiency of the arylsulfatase A enzyme." (PMID 37359369, 2023). "Metachromatic leukodystrophy (MLD) is an autosomal-recessive inherited sphingolipidoses caused by deficiency of the enzyme arylsulfatase-A encoded by the ARSA gene." (PMID 36902174, 2023). "Mutations in IDUA and HGSNAT cause mucopolysaccharidosis I and III types, respectively; mutations in ARSA cause metachromatic leukodystrophy (MLD) that belongs to the sphingolipidosis group." (PMID 38248833, 2023). "Metachromatic leukodystrophy (MLD) is an autosomal recessive lysosomal storage disease caused by deficiency of arylsulfatase A (ARSA)." (PMID 35822086, 2022). "Metachromatic leukodystrophy (MLD) is caused by a failure of myelination homeostasis by a deficiency of the ARSA enzyme in the central (CNS) and the peripheral (PNS) nervous system, leading to demyelination and, consequently, devastating neural manifestations." (PMID 35897729, 2022). "Mutations in the gene encoding the lysosomal enzyme, arylsulfatase A (ASA), causes metachromatic leukodystrophy (MLD), and nine MLD patients were treated with the LV-HSC-ASA gene therapy." (PMID 35745855, 2022). "Metachromatic leukodystrophy (MLD) is a rare inherited lysosomal storage disease caused by deficiency of arylsulfatase A (ARSA), due to mutations in the ARSA gene." (PMID 35065785, 2022). "Metachromatic leukodystrophy (MLD) is a lysosomal storage disease caused by a deficiency of the arylsulfatase A (ARSA)." (PMID 35281658, 2022).
metachromatic leukodystrophy (continued). "Metachromatic Leukodystrophy (MLD) is characterized by mutations in the ARSA gene, leading to deficiency of arylsulfatase and accumulation of sulfatides that are enriched in myelin sheaths." (PMID 35693884, 2022). "Metachromatic leukodystrophy (MLD) is an autosomal recessive lysosomal sphingolipid storage disorder caused by ARSA mutations." (PMID 34082828, 2021). "Metachromatic leukodystrophy (MLD) is an autosomal recessive lysosomal storage disease caused by deficient activity of arylsulfatase A (ASA), resulting in severe motor and cognitive dysfunction." (PMID 33332761, 2021). "Metachromatic leukodystrophy (MLD) is caused by deficiency of lysosomal arylsulfatase A with cerebroside deficiency and sulfatides accumulation in various tissues." (PMID 33801069, 2021). "Metachromatic leukodystrophy (MLD) is a rare lysosomal storage disorder caused by mutations in the gene encoding arylsulfatase A (ARSA)." (PMID 32910272, 2020). "In our data, in addition to APOE, we found that the lipoprotein receptor LSR and the lysosomal enzyme ARSA—a gene in which homozygous mutations cause metachromatic leukodystrophy —were elevated in HAM." (PMID 32610143, 2020). "Loss of arylsulfatase A activity both in metachromatic leukodystrophy patients and in a mouse model of the disease leads to a strong accumulation of sulfatides, a class of lipids enriched in myelin." (PMID 32180696, 2020). "Functional analysis of the mutation in the current study provides a potential pathogenic mechanism of the ARSA mutation in metachromatic leukodystrophy and suggests possible new strategies for diagnosis and treatment." (PMID 32875726, 2020). "In conclusion, we identified a late infantile metachromatic leukodystrophy patient carrying a c.925G>A homozygous mutation in the ARSA gene." (PMID 32875726, 2020). "Arylsulfatase A (ARSA) is a lysosomal acid hydrolase, whose deficiency causes metachromatic leukodystrophy, an autosomal recessive lysosomal storage disease." (PMID 32221382, 2020). "Metachromatic leukodystrophy (MLD) is an autosomal recessive lysosomal disorder owing to ARSA gene mutations resulting in deficiency of the enzyme arylsulfatase A (ASA)." (PMID 30706699, 2019). "In the second case, the homozygous novel variant NM_000487.5:c.256C>G;p.Arg86Gly in the gene ARSA was identified causing metachromatic leukodystrophy." (PMID 30834272, 2019). "Several individuals had a progressive neurological deterioration, including one with juvenile onset metachromatic leukodystrophy, a severe demyelinating disorder caused by recessive mutations in the ARSA gene in 22q13.33." (PMID 31879555, 2019). "Metachromatic leukodystrophy (MLD) is an inherited disease caused by a deficiency of the enzyme arylsulfatase A (ARSA) that leads to severe physiologic and developmental problems." (PMID 30057904, 2018). "Metachromatic Leukodystrophy (MLD) is a rare genetic lysosomal storage disorder (LSD) caused by the functional deficiency of Arylsulfatase A (ARSA; EC 3.1.6.8)." (PMID 29899471, 2018). "ARSA encodes the lysosomal enzyme arylsulfatase A, mutation in this gene was reported in metachromatic leukodystrophy, characterized by progressive demyelination, gait disturbances, ataxias, optical atrophy, dementia, seizures, and spastic tetraparesis." (PMID 27099631, 2016). "Metachromatic leukodystrophy is due to deficiency of arylsulfatase A, an enzyme encoded by the gene ARSA, giving rise to accumulation of urinary sulfatides (prevalence 1/50,000 to 1/170,000, autosomal recessive mode of inheritance)." (PMID 25478001, 2014). "Metachromatic leukodystrophy or scholz's disease is an autosomal recessively inherited lysosomal storage disorder caused by the deficiency of arylsulfatase A (ASA)." (PMID 22284439, 2012). "In metachromatic leukodystrophy (Arylsulfatase A [EC.3.1.6.8] deficiency) storage of the glycosphingolipid sulfatide in the brain leads to demyelination, resulting in neuromotor co-ordination deficits and regression." (PMID 21299873, 2011).
metachromatic leukodystrophy (continued). "Inherited ARSA deficiency causes metachromatic leukodystrophy, a rare lysosomal storage disease whose manifestation ranges from lethality to motor and cognition deficits." (PMID 21966540, 2011). "Metachromatic leukodystrophy (MLD) is a severe neurometabolic disease caused mainly by deficiency of arylsulfatase A encoded by the ARSA gene." (PMID 21695197, 2011). "Homozygous or compound heterozygous ARSA mutations cause metachromatic leukodystrophy (MLD, MIM250100) that displays early, late and adult forms, all with neurological and neuropsychiatric symptoms." (PMID 19492091, 2009). "Arylsulfatase A (ASA)-deficient mice are a model for the lysosomal storage disorder metachromatic leukodystrophy." (PMID 16893448, 2006). "Metachromatic leukodystrophy (MLD) results from ARSA gene mutations." (PMID 37701322, 2023). "Metachromatic leukodystrophy is a lysosomal storage disorder (LSD) caused by decreased levels of Arylsulfatase A (ARSA), an enzyme involved in desulfation of sulfatide, a specific sphingolipid (3-O-sulfogalactosylceramide) that is important for the development and function of OLs and Schwann cells." (PMID 38273973, 2023). "Metachromatic leukodystrophy is an inherited lysosomal disorder caused by recessive mutations in ARSA encoding arylsulfatase A. Low activity of arylsulfatase A results in the accumulation of sulfatides in the central and peripheral nervous system, leading to demyelination." (PMID 35207493, 2022). "Deficiency of arylsulfatase A and B, that are associated with metachromatic leukodystrophy and Maroteaux-Lamy syndrome, respectively, increases sulfatides and sulfated chondroitin 4-sulfate in the CNS, attenuating oligodendrocyte differentiation and neural recovery." (PMID 34720894, 2021). "Finally, ARSA deficiency leads to impaired commitment/maturation of astrocytes and oligodendrocytes besides neurons in Metachromatic Leukodystrophy (MLD)." (PMID 33062642, 2020). "Metachromatic leukodystrophy (MLD) is caused by defective lysosomal arylsulfatase A (ASA)." (PMID 32808655, 2020). "Metachromatic leukodystrophy is due to a deficiency in arylsulfatase A." (PMID 32180696, 2020). "Metachromatic leukodystrophy (MLD) is a rare inherited lysosomal disorder caused by recessive gene mutations in ARSA (OMIM: 607574) and PSAP (Kihara, 1982; Kihara, Fluharty, O'Brien, & Fish, 1982; van Rappard, Boelens, & Wolf, 2015; Schielen, Kemper, & Gelb, 2017)." (PMID 32875726, 2020). "Patients with deletions extending proximal to SHANK3 have one missing copy of ARSA and may develop metachromatic leukodystrophy in the presence of a pathogenic mutation in the remaining ARSA allele." (PMID 31879555, 2019). "Here we describe the genetic variants in the ARSA gene in Sri Lankan patients with metachromatic leukodystrophy (MLD) as it is currently unknown." (PMID 31694723, 2019). "Metachromatic leukodystrophy is a fatal neurodegenerative lysosomal storage disease caused by genetic defects of the ARSA enzyme that currently lacks definitive treatment and might benefit from the development of novel gene/NSC‐based therapeutics." (PMID 28191778, 2017). "This theory was enforced when some patients with DPHL found to be partially deficient of arylsulfatase A, an enzyme which its complete absence causes accumulation of sulfatides in the myelin producing cells and subsequent leukodystrophy (metachromatic leukodystrophy, MLD)." (PMID 25925073, 2015). "Metachromatic leukodystrophy (MLD) is a lysosomal storage disorder caused by biallelic pathogenic variants in the gene encoding arylsulfatase A (ARSA), causing excessive sulfatide accumulation." (PMID 41315317, 2025). "Metachromatic leukodystrophy (MLD) is a rare inherited disorder of lysosomal storage, caused by a deficiency in the arylsulfatase A (ARSA) enzyme, leading to toxic accumulation of sulfatides, which progressively impair motor and cognitive function." (PMID 40407513, 2025).
metachromatic leukodystrophy (continued). "Metachromatic leukodystrophy (MLD) is a rare neurodegenerative disorder due to low arylsulfatase A activity (Arsa, encoded by ARSA)." (PMID 40457575, 2025). "The deficiencies of ARSA or GALC result in the occurrence of metachromatic leukodystrophy (MLD) or Krabbe disease, respectively." (PMID 40054667, 2025). "Background and aims: Metachromatic leukodystrophy (MLD) is a rare lysosomal disease due to arylsulfatase A (ARSA) deficiency." (PMID 40542581, 2025). "Metachromatic leukodystrophy (MLD) is an inherited genetic lysosomal storage disease caused by dysfunction of arylsulfatase A (ARSA) or its activator prosaposin (PSAP)." (PMID 38916435, 2025). "Another case of intracranial pathology was observed in an earlier clinical trial for metachromatic leukodystrophy (MLD), a lysosomal disease caused by a defect in the arylsulfatase A (ARSA) gene." (PMID 38256124, 2024). "Metachromatic leukodystrophy (MLD) is a neuro-metabolic disorder due to arylsulfatase A deficiency, causing demyelination of the central and peripheral nervous system." (PMID 38564053, 2024). "Metachromatic leukodystrophy (MLD) is an autosomal recessive lysosomal storage disease caused by deficiency in arylsulfatase A (ASA) activity arising primarily from ASA gene (ARSA) variants." (PMID 38383398, 2024). "For instance, among genetic mutations linked to known hNDDs, examples include HTT gene mutation in HD, SOD1 in amyotrophic lateral sclerosis, PSEN1, PSEN2, and APP in AD, ARSA gene mutation in metachromatic leukodystrophy (MLD), and others." (PMID 39200370, 2024). "Mutations in the ARSA gene cause the autosomal-recessive disorder metachromatic leukodystrophy (MLD) (OMIM #250100) due to a deficiency of arylsulfatase A activity." (PMID 38248833, 2023). "Metachromatic leukodystrophy (MLD) is also one of the LSDs that results from arylsulfatase A (ARSA) enzyme deficiency and has been targeted by AAV-mediated therapeutic approaches." (PMID 36899921, 2023). "Two families (EP-02 and EP-11) have biallelic variants in ARSA (NM_001085426.2), linked to Autosomal Recessive Metachromatic Leukodystrophy (MLD, OMIM: 250100)." (PMID 37359369, 2023). "Metachromatic leukodystrophy (MLD) is an LSD resulting from deficiency in the lysosomal enzyme arylsulfatase A and causes myelin degeneration in the CNS and peripheral nervous system." (PMID 36066198, 2022). "Metachromatic leukodystrophy (MLD) is a rare, demyelinating lysosomal storage disorder caused by mutations in the arylsulfatase A gene." (PMID 36056437, 2022). "Metachromatic leukodystrophy (MLD) is an autosomal recessive lysosomal disorder caused by deficiency of arylsulfatase A (ARSA), leading to an accumulation of sulfatides." (PMID 35281662, 2022). "Metachromatic leukodystrophy (MLD) is an autosomal recessive lysosomal disorder caused by mutations in the arylsulfatase A gene." (PMID 36056437, 2022). "An autopsy study of two transplanted metachromatic leukodystrophy (MLD) cases found metabolically competent donor macrophages throughout the white matter expressing arylsulfatase A, the deficient enzyme in MLD." (PMID 35966016, 2022). "Metachromatic leukodystrophy (MLD) is an autosomal recessive inherited lysosomal storage disease caused by the deficiency of the lysosomal sulfatide degrading enzyme arylsulfatase A." (PMID 33226437, 2021). "Metachromatic leukodystrophy (MLD) is a lysosomal storage disease caused by an arylsulfatase A (ARSA) deficiency and characterized by severe neurological symptoms resulting from demyelination within the central and peripheral nervous systems." (PMID 34654893, 2021). "An inherited deficiency of arylsulfatase A (ASA) causes the lysosomal storage disease metachromatic leukodystrophy (MLD) characterized by massive intralysosomal storage of the acidic glycosphingolipid sulfatide and progressive demyelination." (PMID 34375644, 2021).